GPER1 (G protein-coupled estrogen receptor 1)
Diseases named in the same sentence as GPER1 in open-access papers (continued):
Sharing a sentence is not in itself a finding about the gene and the disease.
breast carcinoma (continued). "Gossypol exhibited differential sensitivity in breast cancer cell lines, with MDA-MB-231 cells being more responsive than MCF-7 cells, possibly due to overexpression of Bcl-2 protein and slight G-protein coupled estrogen receptor 1 (GPER) expression." (PMID 40940890, 2025). "The novel and complex relationship between GPER-1 and HPG implies a hormonal regulation with important homeostatic effects on general organ development and reproductive tissues, but also on the pathophysiology of cancer, especially breast cancer." (PMID 39936103, 2025). "Further, antiestrogens Ful and Tam induced IGFBP-3 expression in breast cancer cells regardless of subtype, and GPER1 promoted the expression of IGFBP-3 via activation of YAP/TAZ in TNBC cells." (PMID 39619437, 2024). "GPER1 (also known as GPR30), is the second type of estrogen-dependent receptor and is a member of the transmembrane metabotropic receptors family, which was originally detected in breast cancer tissue." (PMID 37835383, 2023). "In breast cancer cells, estrogen regulates IGFBP1 expression via GPER1." (PMID 37907850, 2023). "It is well known that the EGFR-sensitive mutation enhances the phosphorylation of MAPK and Akt in NSCLC, and our previous studies and others had documented that GPER1 can stimulate the phosphorylation of MAPK and Akt through activation of EGFR in breast cancer." (PMID 35664735, 2022). "E2 binds GPER1 with high affinity and this activation leads to ERK phosphorylation, PI3K stimulation, intracellular Ca2+ increase, and cAMP production in the MCF-7 breast cancer cell line, which occurs via trans-activation of the epidermal growth factor receptor and results in proliferation." (PMID 34089761, 2021). "In this sense, experiments carried out by our group on breast cancer cell lines support that continuous pharmacological blockade of classical ERs leads to the overexpression of GPER-1 (non-classical ER) as an alternative pathway to promote proliferation." (PMID 33762910, 2021). "Clinical studies have shown that patients suffering an estrogen receptor α (ERα)/GPER-1 positive, breast cancer have a lower survival rate than those who have developed ERα-positive/GPER-1 negative tumors." (PMID 33117280, 2020). "As few years later, further experimental data showed that in breast cancer cells the synthetic molecule MIBE may bind to and block both ERα and GPER1 activity." (PMID 33374170, 2020). "Therefore, we explored the possibility of molecular interactions between GPER-1 and the kinin B1R, another member of the GPCR family, which is strongly expressed in ERα positive breast cancer cells." (PMID 33117280, 2020). "Moreover, GPER1 signalling triggers HIF-1α-dependent VEGF expression supporting its involvement in angiogenesis and progression of breast cancer." (PMID 33374170, 2020). "Furthermore, Reddel and Sutherland found that 10 nM tamoxifen had a proliferative effect on T47D breast cancer cells, a cell line which like MCF-7 cells expresses both ERα and GPER-1." (PMID 33117280, 2020). "High [D-glucose] will not inactivate AMPK in these cell lines due to genetic background and thus will not reduce GPER1 expression as observed in breast cancer cell lines." (PMID 31242463, 2019). "GPER, also known as GPER1 or GPR30, was first discovered in 1996 in breast cancer tissue." (PMID 31708873, 2019). "The results from these experiments reveal that D-glucose deprivation increased GPER1-mediated and tamoxifen-induced IGFBP-1 transcription suggesting that [D-glucose] may increase breast cancer cell sensitivity to tamoxifen." (PMID 31242463, 2019). "The GPER-1 mRNA levels were significant higher in ER positive breast cancer cells compared to ER negative cancer cells, and the expression of GPER-1 depends on ERα mRNA level." (PMID 27314054, 2016).
breast carcinoma (continued). "The G-protein-coupled estrogen receptor-1 (GPER, formerly known as GPR30) has attracted increasing interest, considering its ability to mediate estrogenic signaling in different cell types, including the hormone-sensitive tumors like breast cancer." (PMID 24834064, 2014). "Therefore, it seems that the role of GPER1 in response to BPA in breast cancer cells is not clear to date." (PMID 41493512, 2026). "However, we and others demonstrated that G-1 abrogates the proliferation of both MCF-7 (ER/GPER1-positive) and MDA-MB-231 (ER/GPER1-negative) breast cancer cells, with more substantial effects on MDA-MB-231 cells than on MCF-7 cells." (PMID 37754248, 2023). "The reduced expression of GPER1 favors cell aggressiveness, such as stimulated cell proliferation, particularly in LTED cells, as indicated in the reports suggesting that GPER1 can act as a tumor suppressor in different types of cancers, including breast cancer." (PMID 37754248, 2023). "However, their interactions with GPER1 and their possible proliferative effects in various types of breast cancer cells or cervical cancer cells had not previously been determined." (PMID 36231664, 2022). "However, the specific modulators for GPER1, which can be used in the clinical treatment of breast cancer, have not appeared." (PMID 34768896, 2021). "GPER-1 was also reported to be activated through estrogen-mediated extracellular signal-regulated kinase 1/2 (ERK1/2) and increase the concentration of cAMP in breast cancers, which further activates protein kinase A (PKA) and phosphorylates cAMP response element-binding protein (CREB)." (PMID 32899453, 2020). "Moreover, absence of GPER-1 improves the prognosis of patients treated with tamoxifen, the most used selective estrogen receptor modulator to treat ERα-positive breast cancer." (PMID 33117280, 2020). "However, more experiments (including silencing of GPR30/GPER-1 with RNAi) are required to determine the exact mechanism of ER negative breast cancer cell proliferation in response to 4-OHT." (PMID 23372829, 2013). "However, GPER1 can activate additional mediators of cell survival, such as extracellular signal-related kinase 1 and 2 (ERK1/2), ELK1, CREB, and FOS that may be involved in IGFBP-3 induction upon Ful treatment in breast cancer cells." (PMID 39619437, 2024). "Likewise, multiple studies have shown that G-protein coupled estrogen receptor 1 (GPER) is also involved in the transduction of estrogenic signals for the regulation of cell growth and proliferation in different types of solid tumors, such as colon cancers, lung, cervix, and breast cancer." (PMID 34066820, 2021). "Note that we did not evaluate the impact of GPER1 overexpression on the localization of PRKCSH, but it has been reported for breast cancer cells that PRKCSH can translocate to the nucleus in a complex with the fibroblast growth factor 1 and its receptor FGFR." (PMID 37947649, 2023).
ovarian carcinoma (75 papers, 2009 to 2025). A malignant neoplasm originating from the surface ovarian epithelium. "In ovarian tissue samples, GPER1 was found to be broadly expressed in high-risk ovarian cancer, associated with lower 5-year survival rates." (PMID 39796024, 2024). "In ovarian cancer, however, high levels of H3K4me3 marks were shown to be associated with high GPER1 expression, leading to a better prognosis of GPER1-positive OC patients." (PMID 39796024, 2024). "It has been shown that GPER-1 acts as a potential tumor suppressor in ovarian cancer, and its high expression is associated with favorable clinical outcomes." (PMID 37106610, 2023). "Smith and co-workers have shown in 89 ovarian cancer patients that GPER-1 expression is associated with poor survival." (PMID 23849542, 2013). "In vitro, GPER-1 stimulation was associated with a significant increase of cellular apoptosis and cell cycle arrest in ovarian cancer cells." (PMID 23849542, 2013). "Loss of GPER-1 expression was more frequently observed in advanced ovarian cancer." (PMID 23849542, 2013). "Consistent with an inhibitory role, G1, a selective GPER‐1 agonist, inhibited the proliferation of ovarian cancer cell lines (SKOV‐3 and OVCAR‐3)." (PMID 40634118, 2025). "In ovarian cancer cells, GPER1 can be detected both within the nucleus and the cytoplasm, and the nuclear GPER1 is a potential predictive factor of poor survival." (PMID 39252786, 2024). "GPER1 is involved in cell growth, proliferation, and differentiation, and has been identified as a biomarker for ovarian cancer diagnosis and prognosis, and a potential target for therapeutic intervention." (PMID 40836974, 2024). "In ovarian cancer, a recent study suggests that GPER1 expression is epigenetically activated by histone H3 trimethylation (H3K4me)." (PMID 39796024, 2024). "The estrogen receptors, ERα, ERβ, and GPER1, are expressed both in normal ovarian tissue and in ovarian cancer." (PMID 39796024, 2024). "An IHC-based study investigating tissue from 45 patients with ovarian tumors of low-malignant potential and 89 patients with ovarian cancers showed a higher expression of GPER1 in tumors of higher stage and grade." (PMID 37345182, 2023). "The latest hints for a link of GPER1 to the centrosome came from studies in rodents and ovarian cancer cells reporting G-1 facilitated the activation of protein kinase A and the phosphorylation of Aurora A kinase, respectively." (PMID 36384894, 2023). "Limited information is available on the impact and role of GPER1 on ovarian cancer, and therefore further studies are required to confirm the tumor-suppressing or proliferating effect of GPER1 before using it as a drug target." (PMID 35625966, 2022). "The higher GPER1 expression in the early stages of ovarian cancer further emphasized its anti-tumor role." (PMID 36060947, 2022). "considered GPER1 a tumor suppressor in ovarian cancer owing to its lower expression in ovarian cancer tissues than in benign tissues." (PMID 36060947, 2022). "The more recently identified G protein-coupled receptor (GPER1; GPR30) has been shown to mediate both tumor-suppressive and tumor-promoting action in ovarian cancer cells, suggesting a more complex role." (PMID 32580290, 2020). "The role of GPER1 in ovarian cancer is somewhat controversial, with differing studies demonstrating opposite outcomes." (PMID 32580290, 2020). "Consistent with a suppressor role, a selective GPER-1 agonist, G1, suppressed the proliferation of ovarian cancer cell lines (SKOV3 and OVCAR3)." (PMID 32580290, 2020). "As for epithelial ovarian cancers, the role of GPER1 is poorly clarified, with different studies producing a mixed picture." (PMID 32580290, 2020). "The inhibition of the EGFR pathway inhibited c-fos and ERK activation, indicating that in ovarian cancer cells, the GPER1/EGFR signaling relies on ERα expression." (PMID 32580290, 2020).
ovarian carcinoma (continued). "The Edu assays showed that the proliferation of AGS and MGC-903 cells was significantly decreased by the GPER1 knockdown, which is consistent with studies in ovarian cancer." (PMID 33425895, 2020). "Atrazine, one of the most common pesticide contaminants, promoted ovarian cancer cells proliferation via induction of Erk and expression of estrogen target gene through GPER-1 pathway." (PMID 27314054, 2016). "The expression of GPER-1 was significantly increased in ovarian carcinomas compared to pericarcinomatous tissues impendent with the expression of EGFR, ERα, and ERβ." (PMID 27314054, 2016). "Henic and co-workers have recently found that GPER-1 stimulation attenuates the invasive properties of ovarian cancer cells." (PMID 23849542, 2013). "It is to note that in this cohort of 150 patients GPER-1 was expressed in only one third, whereas in our cohort more than 80% of the invasive ovarian cancers expressed GPER-1." (PMID 23849542, 2013). "Secondary outcome was the correlation of GPER-1 expression in ovarian cancer tissue and clinicopathological characteristics." (PMID 23849542, 2013). "This is the first report demonstrating the favourable role of GPER-1 in ovarian cancer patients in regard to disease-free survival (DFS)." (PMID 23849542, 2013). "Smith and co-workers have recently found that GPER-1 expression predicts poor survival of ovarian cancer patients, which is in the opposite to our observation." (PMID 23849542, 2013). "We also tested GPER-1 expression in ovarian cancer cells and the effect of GPER-1 stimulation on cell growth." (PMID 23849542, 2013). "GPER-1 expression was correlated to clinicopathological characteristics and clinical outcome of ovarian cancer patients, which was assessed prospectively." (PMID 23849542, 2013). "GPER-1 expression was analyzed by immunohistochemistry in 35 benign ovarian tumors, 35 tumors of low-malignant potential and in 124 ovarian cancers." (PMID 23849542, 2013). "First, GPER-1 specific agonist inhibited ovarian cancer cell proliferation by inducing cell apoptosis and partially cell cycle arrest." (PMID 23849542, 2013). "GPER-1 expression was correlated to the prospectively evaluated disease-free survival of ovarian cancer patients." (PMID 23849542, 2013). "GPER-1 expression and clinical outcome were investigated in a very homogenous cohort of platinum-treated ovarian cancer patients." (PMID 23849542, 2013). "The expression analysis of GPER-1 in ovarian cancer tissue was designed as a prospective monocentre cohort study." (PMID 23849542, 2013). "Next, we compared GPER-1 protein expression with the clinicopathological features of ovarian cancer." (PMID 23849542, 2013). "GPER-1 expression was significantly lower in ovarian cancer compared to the benign and tumors of LMP (p < 0.0001)." (PMID 23849542, 2013). "This study was conducted to evaluate the GPER-1 expression in ovarian cancer and its correlation with progression." (PMID 23849542, 2013). "A third research group has found that GPER-1 expression predicts lower survival of 150 ovarian cancer patients only by co-expression with epidermal growth factor receptor (EGFR)." (PMID 23849542, 2013). "GPER-1 expression was significantly lower in ovarian cancer tissue than in benign and low-malignant ovarian tumors." (PMID 23849542, 2013). "The inhibitory effect of GPER-1 in ovarian cancer cells has been recently well documented and is in accordance to our results." (PMID 23849542, 2013). "Ignatov and colleagues have suggest that GPER‐1 plays a tumor suppressor role in ovarian cancer." (PMID 40634118, 2025). "Furthermore, GPER1 has been reported to inhibit tumor proliferation in colorectal, prostate, and adrenocortical carcinomas, and GPER agonists have demonstrated growth inhibition in ovarian cancer." (PMID 39252786, 2024). "Modulation of GPER1 has been shown to affect ovarian cancer cell growth." (PMID 37834120, 2023).
ovarian carcinoma (continued). "However, GPER1 plays a complex role in ovarian cancer, demonstrating stimulatory and suppressive functions in cancer cells." (PMID 36060947, 2022). "The use of ERα-positive BG-1 ovarian carcinoma cells showed that both 17β-estradiol and G1 (the GPER-1 agonist) induced c-fos expression and up-regulated cyclins D1, E and A. Both GPER1 and ERα were required for c-fos stimulation and ERK activation in response to either G1 or 17β-estradiol." (PMID 32580290, 2020). "Ignatov and colleagues assigned GPER1 a tumor suppressor role in ovarian cancer." (PMID 32580290, 2020). "A study by Zhu and colleagues of 110 patients with epithelial ovarian cancer suggested that nuclear, but not cytoplasmic, GPER1 expression was associated with poor overall survival." (PMID 32580290, 2020). "Indeed a growing body of evidence showed that GPER-1 is strongly associated with different cancer cells proliferation through PI3K signaling pathway, including ovarian cancer and endometrial cancer." (PMID 30836961, 2019). "GPER RNA as well as GPER-1 protein presents in both primary and malignant ovarian tumor tissues." (PMID 27314054, 2016). "In addition, the effect of GPER-1 stimulation in ovarian cancer cells was assayed via its specific agonist G-1." (PMID 23849542, 2013). "GPER-1 emerges as a new tumor suppressor with unsuspected therapeutic potential for ovarian cancer." (PMID 23849542, 2013). "The most important finding of our study is the fact that GPER-1 with its high expression of 80% in ovarian cancer tissue could be an appropriate target for individualized therapy of ovarian cancer." (PMID 23849542, 2013). "GPER-1 expression was a favourable factor regarding 2-year DFS in ovarian cancer patients." (PMID 23849542, 2013). "Second, GPER-1 expression was found to be down-regulated during ovarian cancer tumorigenesis." (PMID 23849542, 2013). "However, the authors stated that EGFR expression in combination with GPER-1 predicts lower survival in patients with ovarian cancer." (PMID 23849542, 2013). "Moreover, we assayed GPER-1 expression on 15 representative tissue samples of ovarian carcinoma with a second antibody against GPER-1 (sc-48524-R, Santa Cruz, Heidelberg, Germany diluted 1:500)." (PMID 23849542, 2013). "The decreased expression of GPER-1 benign and malignant ovarian tumors corroborates the presumption that GPER-1 might be a tumor suppressor." (PMID 23849542, 2013). "We investigated GPER-1 protein expression in benign and malignant ovarian tumors." (PMID 23849542, 2013). "However, there are controversies in the study of GPER1 and its effect on ovarian cancer." (PMID 35625966, 2022). "Then we investigated whether GPER-1 influences the growth of ovarian cancer cells." (PMID 23849542, 2013). "GPER-1 expression was observed in all (100%) benign ovarian tumors, in 34 of 35 (97.1%) tumors of LMP and in 103 of 124 (83.1%) of ovarian cancers." (PMID 23849542, 2013). "The primary outcome of the study was the correlation of GPER-1 expression and the 2-year disease-free survival (DFS) of ovarian cancer patients." (PMID 23849542, 2013). "GPER-1 expression was assessed by immunohistochemistry in 35 benign ovarian tumors, 35 ovarian tumors of low malignant potential (LMP) and 124 ovarian cancers." (PMID 23849542, 2013). "First of all, we analyzed the protein expression of GPER-1 in SKOV-3 and OVCAR-3 ovarian cancer cells by western blot." (PMID 23849542, 2013). "GPER-1 expression was observed in SKOV-3 and OVCAR-3 ovarian cancer cell lines." (PMID 23849542, 2013). "It suggested that G-1 inhibitory effect in SKOV-3 and OVCAR-3 ovarian cancer cells due to specific activation of GPER-1 and not to cytotoxic properties." (PMID 23849542, 2013). "In contrast, Kolkova and co-workers have not found any correlation between GPER-1 expression and survival of 152 patients with ovarian cancer." (PMID 23849542, 2013).
ovarian carcinoma (continued). "In these series GPER-1 expression has not shown any correlation with overall survival of ovarian cancer patients." (PMID 23849542, 2013). "Newly emerging biomarkers for ovarian cancer include epithelial cell adhesion molecule (EPCAM), syndecans, R-spondin, and several G protein-coupled receptors (GPCRs), including the estrogen receptor GPER1, that are currently being investigated in pre-clinical studies." (PMID 40836974, 2024). "As far as we know, the expression of GPER1 in ovarian cancer tissues is not clear." (PMID 37834120, 2023). "Furthermore, GPER-1 promoted the migration and invasion of ovarian cancer cells OVCAR5 which is characterized by negative ERα and positive GPER by increasing the expression MMP-9." (PMID 27314054, 2016). "Interestingly, another research group has not found any correlation between GPER-1 expression on mRNA and protein level with clinical outcome of ovarian cancer patients." (PMID 23849542, 2013). "It is interesting that several other studies showed that G-1, the special agonist of GPER-1, promoted the expression of GPER-1 and inhibited the proliferation of ER negative breast cancer cells, ovarian cancer cells, and prostate cancer cells." (PMID 27314054, 2016).